SPARC (secreted protein acidic and cysteine rich)
Diseases named in the same sentence as SPARC in open-access papers (continued):
Sharing a sentence is not in itself a finding about the gene and the disease.
tumor (572 papers, 2003 to 2026). "These ligands guide the nanoparticles to bind specifically to receptors such as integrins (αvβ3), SPARC (secreted protein acidic and rich in cysteine), and other tumor-associated markers, facilitating receptor-mediated endocytosis." (PMID 41489768, 2026). "The desmoplastic stroma facilitates tumor resistance through pathways such as SPARC (Secreted Protein Acidic and Rich in Cysteine) and Hedgehog signaling, making it a histological hallmark of PDAC." (PMID 40572765, 2025). "EC5 displayed high expression levels of genes related to ECM remodeling (COL4A1,COL4A2,HSPG2,MMP2,SPARC),which have been previously implicated in tumor angiogenesis." (PMID 41394809, 2025). "SPARC secretion is linked to metabolic changes in the tumor microenvironment that promote immune suppression." (PMID 40890836, 2025). "In a murine breast cancer model, stabilin-1 was able to promote tumor growth, and this function was linked to the stabilin-1-mediated scavenging of SPARC." (PMID 39516356, 2024). "Second, the limited availability of tumor tissue for research purposes clearly influenced the ability to reproduce the SPARC expression associations reported in previous studies." (PMID 38137452, 2023). "We detected SPARC expression in tumor cells (42.4%), cancer‐associated fibroblasts (CAFs; 88.1%), tumor‐associated macrophages (77.1%), endothelial cells (75.2%) and tumor‐infiltrating lymphocytes (9.8%)." (PMID 36346290, 2023). "In our study, SPARC rs4958487 was associated with tumor protein expression; patients with the GG genotype presented lower protein expression, both in the stroma and in the epithelium." (PMID 38137452, 2023). "In our study, SPARC was implicated in the biological process of angiogenesis and tumor invasion, migration, and shape change." (PMID 36918772, 2023). "SPARC was most often expressed by myofibroblasts and inflammatory cancer‐associated fibroblasts (CAFs), and fibroblast‐secreted SPARC exhibited a tumor‐promoting role in TNBC." (PMID 36346290, 2023). "This gene encodes a cysteine-rich (SPARC) multifunctional matrix-associated protein, which is associated with context- and cell-type dependent effects, ranging from tumor suppression to tumor cell invasion and metastasis." (PMID 37176114, 2023). "The stimulation of cancer cell motility by Wnt5a, expression of MMPs via SPARC/Osteonectin, and adjustment of collagen fibers are the other agents causing macrophage-mediated tumor invasion." (PMID 37509382, 2023). "SPARC is highly expressed in tumor stroma and tumor-associated fibroblasts in pancreatic cancer, and its overexpression in this compartment is associated with poorer prognosis." (PMID 37509139, 2023). "The SPARC gene plays multiple roles in extracellular matrix synthesis and cell shaping, associated with tumor cell migration, invasion, and metastasis." (PMID 37509139, 2023). "Alternatively, a secreted protein acidic and rich in cysteine (SPARC) can sequester albumin in the tumor stroma and is partially associated with the tumor-specific albumin uptake." (PMID 37836018, 2023). "SPARC is a stromal cell protein, which can be produced by cells associated with tumor stromal cells and has high expression levels in many cancers." (PMID 35252003, 2022). "SPARC has been associated with tumor metastasis based on the alteration of cell shape which facilitates tumor invasion." (PMID 35641855, 2022). "Previous research has shown that SPARC is closely associated with tumor development and plays a vital role in tumor invasion and metastasis." (PMID 35211625, 2022). "In multivariable analysis, there was a significant association between gender, T stage, tumor size, metastasis, adjuvant therapy, and SPARC and OS." (PMID 36452484, 2022). "Conversely, in a multivariable analysis, gender, T stage, tumor size, metastases, adjuvant therapy, and SPARC were significantly associated with OS, whereas high HS expression had only a borderline association with OS (P=0.055)." (PMID 36452484, 2022).
tumor (continued). "Tumor accumulation of Abraxane® is favored by the overexpression of the secreted protein acidic and rich in cysteine (SPARC) in the membrane of the tumor cell, associated with albumin arrest in the microenvironment." (PMID 36015347, 2022). "In detail, high levels of SPARC were significantly associated with PCas while an increase in PD-L1 and Survivin characterized both inflammatory and neoplastic disease." (PMID 34155195, 2021). "SPARC has also been associated with tumor cell proliferation and migration, the epithelial-mesenchymal transition, and the promotion of the tumor microenvironment." (PMID 34064977, 2021). "A previous study found that loss of SPARC was associated with an inflammatory phenotype of tumor-associated macrophages and fibroblasts, with concomitant increased activation of urothelial and stromal NF-κB and AP1 in vivo and in vitro." (PMID 33388091, 2021). "Although here the loss of SPARC results in increased inflammation, the investigators observed increased tumor progression and decreased survival." (PMID 33466303, 2021). "In our previous study, we found that abundant SPARC protein localized in tumor stroma is associated with an aggressive type of EC." (PMID 33579227, 2021). "With the promotion of invasion and tumour formation, changes in SPARC expression are associated with disease progression and poor prognosis." (PMID 32581654, 2020). "High levels of SPARC are often found to be associated with tumor malignity parameters, such as necrosis and hypoxia condition and strongly correlated with poorer post-operative OS." (PMID 32580473, 2020). "For instance, anti-cancer drugs were loaded into mannosylated bovine serum albumin (BSA) NPs to target drug-resistant colon cancer cells and tumor-associated macrophages, which both highly express mannose receptors and SPARC." (PMID 31858848, 2020). "Alternatively, the secreted protein acidic and rich in cysteine (SPARC) was postulated to sequester albumin in tumor stroma and is partly associated with the tumor-specific uptake of albumin." (PMID 31695779, 2019). "Among the numerous players implicated in regulating tumour cell migration and invasiveness, we specifically focused on SPARC protein and miR-29b1." (PMID 31652569, 2019). "It is evident that, in the future, other potential underlying molecular mechanisms of SPARC-mediated HSA accumulation in tumor cells should be investigated for its effective application as a nanocarrier for targeting tumors." (PMID 31695779, 2019). "Some studies indicated that SPARC was a tumor suppressor, but others found that the protein gene was associated with tumor metastasis and invasion by changing the cell shape." (PMID 31040200, 2019). "Using the syngeneic tumor model system in Sparc-deficient mice provided a useful tool not only for phenotypic characterization but also shined the light on novel roles of SPARC as tumor suppressor in OvCa." (PMID 30332737, 2018). "Noteworthy, remodeling of the stromal ECM by cancer-associated fibroblasts is crucial for tumor cell migration and invasion and SPARC has been associated to these events." (PMID 29559981, 2018). "Our findings indicate that the loss of SPARC supports interconnected metabolic plasticity of cancer cells feeding metabolites between pathways for the anabolic growth of tumor cells." (PMID 30332737, 2018). "The continued mystery surrounding the mechanism of Ca2+ associated TRPA1 and SPARC function identifies the needs to continued investigation into Ca2+-dependent signaling in the tumor stroma." (PMID 29636894, 2018). "SPARC is frequently upregulated in tumor tissue and it is implicated to play a role in cancer development and growth." (PMID 29623263, 2018). "One tumor contained a cluster of highly mutated genes (bottom left), including SPARC and FLNA, which are associated with cell-matrix interactions and cell motility, and thus possibly involved in metastasis." (PMID 30083469, 2018).
tumor (continued). "We have reported on the tumor suppressor effect of SPARC in OvCa as both stromal- and tumor-derived SPARC inhibits tumor growth and invasiveness, and are implicated in the normalization of the peritoneal tumor microenvironment (TME)." (PMID 30332737, 2018). "We performed univariable and multivariable analyses to assess the association between plasma SPARC levels and other established clinicopathological parameters such as age, smoking (in terms of packyears), tumor stage and COPD." (PMID 30227835, 2018). "SPARC has been predominantly detected in the tumor-associated stroma, specifically in ECM produced by activated fibroblasts." (PMID 30227835, 2018). "In fact, high levels of SPARC expression within NSCLC tumor tissues, are associated to longer survival, while its absence represents a negative prognostic factor." (PMID 30227835, 2018). "In an in vivo model using SPARC-deficient mice, SPARC exhibited a tumor suppressor function modulating carcinogenesis, progression, and metastasis." (PMID 29065446, 2017). "SPARC is secreted from many types of cancer and tumor-associated stroma cells, and is considered to regulate tumor cell growth and metastasis." (PMID 28718842, 2017). "SPOCK1 belongs to the Ca2+-binding proteoglycan family which includes SPARC, a well-studied tumor-associated component involved in regulating adhesion, matrix cellular interactions, and cell growth." (PMID 28103946, 2017). "It was reported that SPARC was predominantly found in the tumour-associated stroma, specifically in the cytoplasm and ECM of stromal fibroblasts." (PMID 29262657, 2017). "The role of SPARC seems to depend on the cancer type: it is associated with highly aggressive tumor phenotypes in some cancer, but in others it appeared as a tumor suppressor." (PMID 28425924, 2017). "SPARC overexpression is strongly associated with tumor metastasis in many different cancers and promotes cancer cell invasion." (PMID 26926673, 2016). "Overexpression of SPARC, a collagen-binding glycoprotein, is strongly associated with tumor invasion through extracellular matrix in many aggressive cancers." (PMID 26926673, 2016). "Several studies have demonstrated that high SPARC expression is associated with small tumor size, low histological grade, and high ER expression (all P < 0.0001), which are all features of slow growing and low proliferating tumors." (PMID 27421134, 2016). "In 78 previously untreated GC patients (group B), higher SPARC expression in postoperative tumor tissue was significantly associated with depth of invasion, lymph node metastasis and TNM stage (P<0.05)." (PMID 25859409, 2015). "Considering that PTX has been proved to be a substrate of P-gp, and once injected into the body, Abraxane quickly decomposed into smaller albumin-paclitaxel complexes and enters tumor cells through association with tumor derived SPARC protein." (PMID 26182353, 2015). "In contrast, other studies have reported downregulation of SPARC in several tumor types, often in association with promoter hypermethylation, and its expression levels to be negatively correlated with tumor stage, therapeutic response or patient outcome." (PMID 25331979, 2014). "The importance of the interactions between neoplastic cells and tumoral environment is highlighted by the associations of stromal expression of SPARC with tumor progression and patient outcome." (PMID 25331979, 2014). "Serum protein acidic and rich in cysteine (SPARC) is a matricellular secreted glycoprotein that performs several cellular functions and has been implicated in tumorigenesis in a variety of tumor types." (PMID 24484617, 2014). "Subgroup analysis showed that patients with either basal or HER2 subtype and high SPARC expression had a higher risk of relapse even after adjusting for tumor size, nodal status, histological grade and age." (PMID 23638089, 2013). "In fact, aberrant SPARC expression was detected both in stromal cells associated with cancer and in tumor cells." (PMID 24396828, 2013).
tumor (continued). "High SPARC expression was associated with small tumor size, low histological grade and luminal-A tumors (all p<0.0001)." (PMID 23638089, 2013). "For example, in cancer, SPARC can act as a tumor suppressor in some tumors, while in others, it is linked with a highly aggressive tumor phenotype." (PMID 23349702, 2013). "Tumor responses to albumin-bound paclitaxel have already been linked to SPARC expression in some tumors." (PMID 23895135, 2013). "Immunohistochemical detection of SPARC protein in tumor cells is associated with survival in meningiomas, tongue carcinoma, head and neck cancer and cutaneous malignant melanomas." (PMID 22321704, 2012). "Similar to SPARC, TGFβ is a multifunctional signaling protein implicated in wound-healing and fibrosis as well as tumor progression and metastasis." (PMID 22348081, 2012). "Our results provide evidence that enhanced metastasis and decreased survival of tumor bearing SPARC-deficient mice is a result of aberrant activation of TGFβ1." (PMID 22348081, 2012). "In the patients here, higher SPARC expression was significantly associated with tumor progression (metastasis and poor prognosis) and the advanced stages of NPC." (PMID 22321704, 2012). "Although we discovered many changes in the tumor microenvironment of SPARC−/− compared to SPARC+/+ animals, the underlying cause for increased invasion/metastasis and decreased survival remained elusive." (PMID 22348081, 2012). "The data underlie the importance of SPARC (produced by host leukocytes) in the assembly and organization of tumor stroma." (PMID 24213109, 2011). "It was also determined that the antiangiogenic effects of SPARC were associated with reduced tumor levels of VEGF." (PMID 20671917, 2010). "The results showed that both SPARC gene expression and secretion levels were negatively associated with the metastatic capacity of tumor cells." (PMID 20687958, 2010). "In cancer, SPARC can be not only associated with a highly aggressive phenotype, but also acts as a tumour suppressor." (PMID 19920824, 2010). "Further, inhibition of MMP-9 expression caused SPARC-mediated inhibition of angiogenesis and tumour growth as MMP-9 rescued SPARC-mediated anti-angiogenic effect in vitro and tumour growth inhibition in vivo." (PMID 20087345, 2010). "The reduced tumour growth in tumours formed with Daoy cells expressing SPARC cDNA was associated with a decrease in angiogenesis." (PMID 20087345, 2010). "We designed conditionally replicative adenoviruses based on a specific segment of the SPARC promoter with the aim to target both malignant and tumor-associated stromal cells." (PMID 19337591, 2009). "SPARC is produced by different cell types including malignant cells and tumor associated stromal cells such as fibroblast and endothelial cells." (PMID 19337591, 2009). "Numerous studies have reported SPARC to be up regulated in endothelial cells, to have a role in tissue remodelling and be linked to tumour progression." (PMID 18394197, 2008). "Our computer-based screen revealed four UTR-SNPs located in the 3'-UTR of SPARC (1474 g→a, 1551 g→c, 1922 t→g and 2072 c→t) that were significantly associated with tumor libraries." (PMID 17201911, 2007). "Additionally, the secreted protein acidic and rich in cysteine (SPARC) captures albumin within the tumor stroma, which is associated with tumor-specific albumin uptake." (PMID 41002483, 2025). "Notably, SPARC has previously been linked to acquired tumor cell invasion abilities, a process often facilitated by a suppressed immune response." (PMID 40528051, 2025). "Finally, for further validation, we analyzed another pair of tumor cell lines derived from SPARC-null HER2Neu transgenic mice and their SPARC-transduced coisogenic variants, SN25A and SN25ASP." (PMID 40890836, 2025).
tumor (continued). "Albumin binding to SPARC expressed in tumor tissue has also been implicated in increased accumulation of albumin-binding therapeutics, and we found that SPARC is expressed in both EMT6 and B16.F10 tumors and may therefore contribute to nAlb accumulation." (PMID 38766114, 2024). "We also found correlations with three other SPARC variants and SPARC expression, suggesting that the variants could provide information regarding protein expression in tumor tissue." (PMID 38137452, 2023). "Studies using IHC reported that SPARC expression in tumor cells was associated with prognosis." (PMID 36346290, 2023). "For instance, Secreted Protein Acidic and Rich in Cysteine (SPARC) is distinctly expressed in various cells, including tumor cells, cancer-associated fibroblasts (CAFs), tumor-associated macrophages, endothelial cells, and tumor-infiltrating lymphocytes." (PMID 37988189, 2023). "SPARC was found to be synthesized and secreted by tumor stromal cells, and its expression was associated with an acidic environment and the necrosis of tumor tissues, as its expression levels were higher in tumor necrosis areas." (PMID 35211625, 2022). "Furthermore, DCN, ITGB1, NOTCH3 and SPARC genes were discovered to be strongly associated not only with tumor response to nCRT but also with disease-free survival; they were further used to form a four-gene expression-based risk score." (PMID 35682714, 2022). "In addition, GLA has been reported to decrease the expression of the metastasis-associated protein osteonectin (or SPARC) and increase the expression of metastasis suppressor genes to inhibit tumor metastasis." (PMID 36090329, 2022). "However, although upregulated SPARC expression is thought to be associated with a favorable outcome, the functional role of SPARC in cancer varies according to tumor type and tissue environment." (PMID 35981080, 2022). "Uptake of albumin conjugates are presumably mediated by gp60 transcytosis pathway and subsequent specific binding to secreted protein acidic and rich in cysteine (SPARC) in tumor interstitium, and overexpression of SPARC is associated with enhanced tumor invasion, metastasis and thus poor prognosis." (PMID 35456631, 2022). "In univariate Cox regression using continuous values, higher FAP expression (HR = 1.01, p = 0.03, corrected P value = 1.00) and higher SPARC expression (HR = 1.07, p = 0.006, corrected P value = 0.21) in tumor stroma were associated with shorter survival in MPM patients." (PMID 33955203, 2021). "And moreover, hypomethylation in SPARC promoter might be a cause of its increased expression in LIHC tumor tissues." (PMID 34912848, 2021). "Binding of SPARC to albumin causes release of free drug, which permeates into tumor cells." (PMID 31858848, 2020). "The silencing of SPARC (secreted protein acid and rich in cysteine) gene through methylation of its promoter region represents a common event in many solid tumors and it is frequently associated with tumor progression and an aggressive clinical outcome." (PMID 32580473, 2020). "The SPARC protein product has been associated with a variety of cancers, including GC; it may affect GC metastasis by regulating the tumor microenvironment." (PMID 32908877, 2020). "In contrast, SPARC methylation status did adequately discriminate patients with lower and higher disease outcomes risk both in the overall sample and within those with early tumor stage." (PMID 32580473, 2020). "However, SPARC has also been implicated in oncologic studies playing a prominent role in both tumorigenesis and tumor suppression." (PMID 31014251, 2019). "These cells have the intrinsic ability to secrete SPARC when exposed to mechanical stress, such as that caused by RhoA-induced actomyosin constriction, which enables them to migrate away from the cell-dense and nutrition-deprived bulk of the tumor." (PMID 31062076, 2019). "The upregulation of SPARC was associated with tumor metastasis and poor prognosis in GC." (PMID 31218131, 2019).